GDF2 (growth differentiation factor 2)
Description:
Potent circulating inhibitor of angiogenesis. Signals through the type I activin receptor ACVRL1 but not other Alks. Signaling through SMAD1 in endothelial cells requires TGF-beta coreceptor endoglin/ENG.
Synonyms: BMP-9; BMP9; HHT5
Tractability: Small molecule: a structure with a bound ligand is known. Antibody: UniProt places it where antibodies can reach, with high confidence; its Gene Ontology location is reachable by antibodies, with high confidence; UniProt predicts a signal peptide or a membrane-spanning region. Other modalities: a drug acting on it is in phase 2 or 3 trials.
Target class: Secreted protein
Gene: Protein-coding gene on chromosome 10 (47,322,454 to 47,327,588, forward strand). Ensembl gene ENSG00000263761.
Subcellular location: Secreted
Pathways (Reactome):
Signal Transduction: Signaling by BMP
Gene Ontology:
Molecular function: cytokine activity; growth factor activity; protein binding
Biological process: activin receptor signaling pathway; angiogenesis; blood vessel morphogenesis; BMP signaling pathway; branching involved in blood vessel morphogenesis; cellular response to BMP stimulus; negative regulation of cell growth; negative regulation of endothelial cell migration; negative regulation of endothelial cell proliferation; positive regulation of angiogenesis; positive regulation of bicellular tight junction assembly; positive regulation of DNA-templated transcription; positive regulation of endothelial cell proliferation; positive regulation of epithelial cell differentiation; positive regulation of interleukin-8 production; positive regulation of Notch signaling pathway; positive regulation of SMAD protein signal transduction; positive regulation of transcription by RNA polymerase II; cartilage development; intracellular iron ion homeostasis; negative regulation of angiogenesis; negative regulation of blood vessel endothelial cell migration; negative regulation of DNA replication; ossification; positive regulation of BMP signaling pathway; and 5 more
Cellular component: extracellular exosome; extracellular region
Genetic constraint (gnomAD): Loss-of-function variants: 19 observed, 23.08 expected, observed/expected ratio (o/e) 0.82, 90% interval 0.57 to 1.21. The upper end of that interval is the gene's LOEUF score, 1.21, which puts it in group 5 of 6, group 1 being the genes least tolerant of losing a copy. Missense variants: 523 observed, 572.82 expected, observed/expected ratio (o/e) 0.91, 90% interval 0.85 to 0.98. Synonymous variants: 276 observed, 243.03 expected, observed/expected ratio (o/e) 1.14, 90% interval 1.03 to 1.25.
Gene-disease validity (ClinGen):
ClinGen rates the evidence that GDF2 causes each of these diseases.
pulmonary arterial hypertension (autosomal dominant): Definitive. Pulmonary arterial hypertension (PAH) is a group of diseases characterized by mean pulmonary artery pressure >20 mmHg and elevated pulmonary arterial resistance leading to right heart failure.
telangiectasia, hereditary hemorrhagic, type 5 (autosomal dominant): Moderate.
Homologues: Orthologues: chimpanzee GDF2 (99% identical), macaque GDF2 (96% identical), pig GDF2 (82% identical), rat Gdf2 (81% identical), mouse Gdf2 (80% identical), rabbit GDF2 (79% identical), guinea pig GDF2 (76% identical), dog GDF2 (74% identical), tropical clawed frog gdf2 (41% identical), zebrafish gdf2 (37% identical). Paralogues in human: BMP10 (38% identical), BMP4 (29% identical), BMP2 (28% identical), BMP6 (27% identical), GDF6 (27% identical), BMP8A (26% identical), BMP8B (26% identical), BMP5 (26% identical), BMP7 (25% identical), GDF7 (24% identical), GDF5 (23% identical), NODAL (21% identical), and 19 more.